RAD21L1 (RAD21 cohesin complex component like 1)
Description:
Meiosis-specific component of some cohesin complex required during the initial steps of prophase I in male meiosis. Probably required during early meiosis in males for separation of sister chromatids and homologous chromosomes. Replaces RAD21 in premeiotic S phase (during early stages of prophase I), while RAD21 reappears in later stages of prophase I. Involved in synaptonemal complex assembly, synapsis initiation and crossover recombination between homologous chromosomes during prophase I (By similarity).
Synonyms: RAD21L; dJ545L17.2
Tractability: PROTAC: ubiquitination databases record sites on it.
Gene: Protein-coding gene on chromosome 20 (1,226,027 to 1,296,421, forward strand). Ensembl gene ENSG00000244588.
Subcellular location: Nucleus; Chromosome
Gene Ontology:
Molecular function: chromatin binding
Biological process: establishment of meiotic sister chromatid cohesion; replication-born double-strand break repair via sister chromatid exchange; sister chromatid cohesion
Cellular component: chromosome; meiotic cohesin complex; nucleus; cohesin complex
Genetic constraint (gnomAD): Loss-of-function variants: 10 observed, 14.05 expected, observed/expected ratio (o/e) 0.71, 90% interval 0.44 to 1.21. The upper end of that interval is the gene's LOEUF score, 1.21, which puts it in group 5 of 6, group 1 being the genes least tolerant of losing a copy. Missense variants: 190 observed, 206.99 expected, observed/expected ratio (o/e) 0.92, 90% interval 0.81 to 1.03. Synonymous variants: 60 observed, 70.98 expected, observed/expected ratio (o/e) 0.85, 90% interval 0.69 to 1.05.
Homologues: Orthologues: chimpanzee SNPH (99% identical), macaque RAD21L1 (95% identical), dog RAD21L1 (85% identical), guinea pig RAD21L1 (76% identical), mouse Rad21l (73% identical), rat Rad21l1 (73% identical), Drosophila melanogaster vtd (40% identical). Paralogues in human: RAD21 (48% identical), REC8 (19% identical).
Diseases named in the same sentence as RAD21L1 in open-access papers:
RAD21L1 is named in the same sentence as 9 diseases in open-access papers, as found by Europe PMC text mining. Sharing a sentence is not in itself a finding about the gene and the disease. The quoted sentences say what the papers report.
infertile (4 papers, 2016 to 2025). "Although it is not known whether the remaining genes may lead to female infertility, it is noteworthy that in seven of them (ADAD2, AR, C1orf146, MLH3, RAD21L1, SYCP3, and TERB1), the corresponding female KO mice are infertile." (PMID 40896145, 2025).
Azoospermia (3 papers, 2021 to 2025). Absence of any measurable level of sperm,whereby spermatozoa cannot be observed even after centrifugation of the semen pellet. "This is consistent with a single-nucleotide polymorphism in human RAD21L1 linked to azoospermia in Sertoli cell-only syndrome in males." (PMID 34138874, 2021). "Notably, RAD21L1 mutations are positively related to risk of non‐obstructive azoospermia (NOA) and male infertility." (PMID 41098129, 2025).
male infertility (2 papers, 2023 to 2025). The inability of the male to effect fertilization of an ovum after a specified period of unprotected intercourse. "Significantly, we found that RAD21L1 mutations were closely associated with the risk of NOA and male infertility." (PMID 41098129, 2025).
Cornelia de Lange syndrome (1 paper, 2022). A rare syndrome characterized by low birth weight, delayed growth, intellectual disabillity, behavioral problems, and a distinctive facial appearance (thin, arched eyebrows, low set ears, small teeth, and small nose). "Mutations of the human ortholog of vtd, RAD21L1 (RAD21-like 1) cause a mild Cornelia de Lange syndrome phenotype." (PMID 36231024, 2022).
tumor (2 papers, 2012 to 2021). "A body of emerging evidence has revealed that meiotic chromosome regulator genes, including REC8, SMC1β, RAD21L1, TEX19, HORMAD1, and SYCP3, are inappropriately activated to modulate chromosome maintenance and segregation in tumor development, maintenance, and spread." (PMID 34150762, 2021).
RAD21L1 also shares sentences with these, for which no sentence is quoted: cancer (3 papers); Sertoli Cell-Only Syndrome (2); Fanconi anemia (1); female infertility (1).